MTOR (mechanistic target of rapamycin kinase)
Diseases named in the same sentence as MTOR in open-access papers (continued):
Sharing a sentence is not in itself a finding about the gene and the disease.
breast cancer (continued). "The progression and recurrence of HER2-positive breast cancer are supported by HER2-Akt-mTOR signaling that promotes pro-survival signaling and cell cycle progression." (PMID 34208071, 2021). "In summary, the results of our study and data available on the international database TCGA indicated that the PI3K/Akt/mTOR pathway plays an important role in breast cancer." (PMID 33669698, 2021). "We analyzed the data present on the PI3K/Akt/mTOR pathway in breast cancer available on international databases—The Cancer Genome Atlas—and compared them with our own research." (PMID 33669698, 2021). "A breast cancer study identified Akt/mTOR as being a major component of successful metastatic colonization of the lungs." (PMID 34831037, 2021). "Activation of PI3K/Akt/mTOR signaling stimulates cell motility and initiates the metastatic phenotype of breast cancer cells." (PMID 34579037, 2021). "As a downstream molecule of the PI3K/AKT pathway, mTOR inhibitors can inhibit breast cancer cell growth." (PMID 33790792, 2021). "For instance, the upregulation of the PI3K/AKT/mTOR pathway was observed in 70% of ovarian cancers and 30–40% of breast cancers." (PMID 34832087, 2021). "It has been reported that quercetin suppresses the mobility of breast cancer by the inhibition of glycolysis through the Akt-mTOR pathway and the activation of autophagy." (PMID 34744708, 2021). "This is in agreement with studies reporting a dominant modification in receptor tyrosine kinase signaling via the Akt-mTOR pathway in homotypic 3D cultures modeling colon and breast cancer." (PMID 34208775, 2021). "CEBPD has been implicated in MTOR signalling enhancement by transcriptionally suppressing FBXW7, leading to mammary tumour metastasis." (PMID 34954904, 2021). "Combination of everolimus (mTOR inhibitor) with endocrine therapy is also a breakthrough treatment strategy for previously aromatase inhibitor-treated advanced breast cancer." (PMID 33841325, 2021). "MicroRNA-184 modulates the PI3K/Akt/mTOR signaling pathway and miR-124, a potential oncogenic in breast cancer targets PTEN-PI3K/Akt pathway." (PMID 33916931, 2021). "Increased expression of COL17 in breast cancer cells reduces the expression of the proliferative marker Ki67 and deactivates mTOR signaling molecules by dephosphorylation of AKT, mTOR, and effector molecules, including p70S6K and particularly 4EBP1." (PMID 34293053, 2021). "Collectively, these results suggest that CSNK1G2 plays a key role in sensitizing TAM toxicity in ER+ and ER- breast cancer cells via differently regulating PI3K/AKT/mTOR/S6K and ERK signaling." (PMID 33861751, 2021). "The pathways involved in the progression of breast cancer were the MTOR signaling pathway, estrogen signaling pathway, P13-AKT signaling pathway, TGF-β signaling pathway and the insulin signaling pathway." (PMID 33593445, 2021). "Taken together, activation of the PI3K/Akt/mTOR pathway plays a central role in breast cancer, and blocking of this pathway is an attractive treatment target, especially in endocrine-resistant ER-positive breast cancer." (PMID 33841325, 2021). "In summary, for the first time, we demonstrated that ICJ extracted from the traditional Chinese herb Stellera chamaejasme L. reduced metastatic colonization in breast cancer cells by inhibiting the AKT/mTOR pathway in TAMs." (PMID 35027915, 2021). "Among these, IGF1 activates phosphoinositide 3-kinase (PI3K)/Akt mammalian target of rapamycin (mTOR) pathway, with subsequent breast cancer cell growth, proliferation, and migration into the bone." (PMID 34199522, 2021).
breast cancer (continued). "The presence of BCSCs is also an important cause of ET resistance in luminal breast cancer, which can be regulated by the cyclin-dependent kinase 4/6 (CDK4/6) complex and mechanistic target of rapamycin (mTOR) signaling." (PMID 33672204, 2021). "The PI3K/Akt/mTOR pathway, which is known to interact with the ER pathway, was reported to be frequently upregulated in aromatase inhibitor (AI)-resistant breast cancer." (PMID 34503187, 2021). "SiRNA-mediated depletion of SNRPD1 leads to a significant reduction in cell viability in breast cancer, lung cancer, and leads to autophagy by mTOR pathway." (PMID 34130650, 2021). "In this review, we summarize the current knowledge of the PI3K/AKT/mTOR pathway related to drug resistance in breast cancer and propose an effective drug development strategy." (PMID 33790792, 2021). "Conclusively, these data indicate that GABARAP suppresses the malignant behaviors of breast cancer likely via the AKT/mTOR pathway." (PMID 33591943, 2021). "Here we summarize the most recent advances in the inhibition of the PI3K/AKT/mTOR signaling pathway in breast cancer." (PMID 34298731, 2021). "Taken together, these data suggest a functional role of AKT/mTOR signaling for proliferation and migration in bone-metastatic 231-BO breast cancer cells." (PMID 33670586, 2021). "Taken together, our results suggest that DEPTOR knockdown suppresses cell proliferation and survival by inactivating the PI3K/AKT/mTOR pathway to induce apoptosis in ErbB2-positive breast cancer cells." (PMID 33995662, 2021). "As a consequence, the mTOR inhibitor Everolimus is already approved and used for treatment of advanced breast cancer." (PMID 33670586, 2021). "The results indicated that GABARAP also inhibited the EMT of breast cancer cells via the AKT/mTOR pathway in vivo." (PMID 33591943, 2021). "Several inhibitors have been approved by the US Food and Drug Administration (FDA), including alpelisib (PI3K inhibitor) and everolimus (mTOR inhibitor) in breast cancer." (PMID 34783291, 2021). "For this reason, the effects of both MeJA and MeJA‐treated Col gl1 on mTOR in T‐47D breast cancer cells were examined." (PMID 33124043, 2021). "DEGs were subjected to functional analysis using Gene Ontology (GO) and the KEGG database which identified many transduction pathways associated with breast cancer, including the PI3K/AKT, PTEN and mTOR pathways." (PMID 33599863, 2021). "We predicted that OSI-027 (mTOR inhibitor) is a breast cancer specific drug with high specificity for the Her2-positive subtype breast tumors." (PMID 33858332, 2021). "BBR induces autophagic cell death and apoptosis in human gastric cancer, glioblastoma multiforme (GBM), breast cancer, and hepatoma cells by the activation of Beclin1, as well as the inhibition of the mTOR signaling pathway." (PMID 34575981, 2021). "PTX3 interacts with the PI3K/AKT/mTOR signaling pathway or the fibroblast growth factor-2/receptor system to regulate tumor cell proliferation, apoptosis, and metastasis in lung cancer, breast cancer, melanoma, prostate cancer, and multiple myeloma." (PMID 34745101, 2021). "The decrease in S6K1 and AKT phosphorylation upon DEPTOR silencing suggested that the reduction in the levels of ErbB2 by DEPTOR knockdown appears to play a major role in suppressing the PI3K/AKT/mTOR pathway in ErbB2-positive breast cancer cells." (PMID 33995662, 2021). "The PI3K/Akt/mTOR signaling pathway has been found to be hyperactive in almost all tumors, including breast cancer." (PMID 34953500, 2021). "Decreased PI3K, AKT, and mTOR phosphorylation were also observed in human breast cancer cells at 50 μM for 48 h." (PMID 33918290, 2021).
breast cancer (continued). "Currently, studies are being conducted on the presence of mutations and changes in the expression of the PIK3CA, AKT and mTOR genes in breast cancer; however, the results of these studies are still inconclusive and require further experiments." (PMID 33669698, 2021). "Metformin also induces autophagy through the activation of AMPK/mTOR pathway in multiple myeloma and breast cancer, also in other cell types and animal models." (PMID 33652909, 2021). "Recent database publications demonstrated the possible mechanisms of miR-491-5p in suppressing the migration and invasion of breast cancer by targeting ZNF-703 to regulate the AKT/mTOR pathway or via TPX2 targeting." (PMID 34395516, 2021). "It has been reported that levobupivacaine inhibits cell survival by suppressing the Akt/mTOR signaling in breast cancer cells." (PMID 34177591, 2021). "Currently, a number of drugs targeting PI3K/AKT/mTOR are being investigated in clinical trials by combining them with standard therapies to overcome acquired resistance in breast cancer." (PMID 33790792, 2021). "MiR-424-5p has been shown to reduce cell viability by modulating the PTEN/PI3K/AKT/mTOR pathway in breast-cancer cells, the MAPK pathway in ischemic stroke, and the Hippo-signaling pathway in thyroid cancer." (PMID 33477683, 2021). "DPP-4 inhibitor-induced breast cancer metastasis was attenuated by the CXCR4 inhibitor AMD3100, with the suppression of genes associated with EMT and a mammalian target of rapamycin (mTOR) signaling pathway in the primary tumor." (PMID 34063285, 2021). "Accordingly, the depletion of SALL2 decreased ESR1 and PTEN expression, activated the Akt/mTOR signaling, and resulted in estrogen-independent growth and tamoxifen resistance in ERα-positive breast cancer." (PMID 34944911, 2021). "Evidence has shown that flavonoids induce autophagy and apoptosis and inhibit cell proliferation through downregulation of the PI3K-mediated PI3K/AKT/mTOR signaling pathway in human breast cancer, including MDA-MB-231 TNBC cells." (PMID 33916931, 2021). "The expression of GAS5 is increased by mTOR inhibitors, which are now widely used in clinical practice and have been proposed to improve the responses to chemotherapy in breast cancer." (PMID 34202777, 2021). "These genes were enriched in breast cancer cells, as well as in the mTOR, AMPK, and Wnt signaling pathways." (PMID 34203447, 2021). "Curcumin was found to inhibit the phosphorylation of Akt, mTOR and their downstream proteins, resulting in cell cycle arrest of various breast cancer cell lines, including T47D and MCF7." (PMID 34572272, 2021). "It has been reported to suppress cell proliferation and induce the G2/M phase cell cycle arrest by inhibiting the PI3K/Akt/mTOR pathway in colorectal and breast cancer." (PMID 34830339, 2021). "Like dual inhibition of estrogen and mTOR or CDK4/6 in recurrent/metastatic ER-α/PgR-positive breast cancer, the possibility of dual inhibition of androgen and mTOR or CDK4/6 is now attracting interest in TNBC." (PMID 34070471, 2021). "The mTOR pathway is important for driving EMT processes in a mammary tumor, and mTOR inhibition suppresses breast cancer proliferation, migration and metastasis." (PMID 34063285, 2021). "Dysregulation of these functions belongs to the disease characteristics of cancer and the PI3K/AKT/mTOR pathway has been identified as a key player driving carcinogenesis in various tumor entities such as breast cancer and renal cell carcinoma." (PMID 33807050, 2021). "The large-scale comprehensive molecular landscape of breast cancer carried out by The Cancer Genome Atlas Network demonstrated a clear picture of PI3K/AKT/mTOR signaling pathway in TNBC, more precisely, in the basal-like breast cancer subtype." (PMID 34888495, 2021). "Mechanically sensitive caveolin-1 activation induces the PI3K/Akt/mTOR signaling pathway to promote motility and invasive in vivo formation, and metastasis of breast cancer." (PMID 34540654, 2021).
breast cancer (continued). "In ER+ breast cancer cells that are resistant to CDK4/6 inhibitors, the mammalian target of rapamycin (mTOR) pathway is commonly mutated." (PMID 34830174, 2021). "This suggests that mTOR hyperactivation is a critical contributor to the elevated glycolytic activity observed in HER2-positive breast cancer." (PMID 34208071, 2021). "In fact, PI3K/Akt/mTOR pathway has been demonstrated to play a critical role in survival and proliferation of the more resistant putative breast cancer stem cell population." (PMID 34207464, 2021). "For further details of the clinical efficacy of mTOR inhibitors in cancers other than HER2-positive breast cancer, please refer to reviews:." (PMID 34208071, 2021). "At the same time, hypoxia can induce MiR-153 to fine-tune HIF1α/VEGFA in breast cancer angiogenesis, MiR-100 can inhibit in vitro angiogenesis by regulating the mTOR/HIF-1α/VEGF signal transduction axis in breast cancer cells." (PMID 34857023, 2021). "It has been established that the RAS/RAF/MEK/ERK pathway and PI3K/AKT/mTOR pathway are closely interconnected components and form feedback loops in breast cancer." (PMID 33577560, 2021). "The aim of our study was to evaluate the efficacy of three different mTOR inhibitors in in vitro models of trastuzumab-resistant breast cancer cells to assess their potential use in both primary resistance and the development of acquired resistance." (PMID 34204960, 2021). "Treatment with BEZ235, a PI3K and mammalian target of rapamycin (mTOR) inhibitor, promoted apoptosis in ER+ breast cancer cells." (PMID 34769309, 2021). "An example of cooperative growth pathways for mTOR and Wnt was demonstrated in breast cancer cells in transgenic mice overexpressing the glycoprotein Nmb, having increased β-catenin transcriptional activity and phosphorylation of mTOR and 4E-BP1." (PMID 33668092, 2021). "A previous study showed that dual inhibition of PI3K/mTOR in BEZ235-resistant breast cancer cells triggered a positive feedback response and activated the JAK2/STAT5 pathway, resulting in increased IL-8 secretion and drug resistance." (PMID 33431808, 2021). "Here, with a case-control design, we evaluated the associations of body fatness, measured by BMI, waist circumference (WC), WHR, percent body fat, and fat mass index, with breast cancer by the expression level of p-mTOR, which is evidence of mTOR activation." (PMID 34330319, 2021). "The Akt/mTOR-dependent pathway is a leading signaling pathway in the proliferation of breast cancer cells, and clinical evidence suggests that targeting of this pathway is a promising treatment option." (PMID 34572272, 2021). "The PI3K catalytic subunit inhibitor BKM120, the mTOR inhibitor RAD001, and the dual PI3K/mTOR inhibitor BGT226 were tested against ER+ breast cancer cell lines before and following long-term estrogen deprivation (LTED)." (PMID 34769309, 2021). "Collectively, these experiments support the combination of trastuzumab with PI3K/AKT/mTOR inhibitors as a potential strategy for inhibiting the proliferation of HER2-positive breast cancer cell lines that show resistance to trastuzumab." (PMID 34204960, 2021). "UBE2O expression is amplified and relates to AMPKa2/mTOR/HIF1a in human cancers, using the existing microarray database: Liu’s BCa, breast carcinoma (GEO: GSE22820, n = 176); Stephenson’s CaP, prostate carcinoma (n = 97); Taylor’s CaP (GEO: GSE21032, n = 179)." (PMID 34451875, 2021). "The phosphatidylinositol 3-kinase/protein kinase B/mammalian target of rapamycin (PI3K/mTOR) pathway is frequently altered in breast cancer (BC)." (PMID 34069042, 2021).
breast cancer (continued). "In breast cancer cells, mTOR is targeted for ubiquitination and consequent degradation by binding to tumor-suppressing E3 ligase, FBXW7." (PMID 32131492, 2020). "In this study, we reveal that mTOR inhibitors unexpectedly induce breast cancer cell plasticity by enabling the translation of NANOG, SNAIL, and NODAL isoforms in a manner similar to hypoxia." (PMID 32427827, 2020). "The PI3K/AKT/mTOR-signaling pathway has been well documented as playing a major role in carcinogenesis in breast cancer cells." (PMID 32606352, 2020). "The best example so far is everolimus, an mTOR inhibitor registered for the treatment of ER+/HER2− advanced breast cancer." (PMID 31976581, 2020). "In contrast to mTOR canonical inhibitors, treatment of ErbB2 breast cancer by MEDICA allows for both, inhibition of mTORC1 activity while concomitantly disrupting ErbB family members and their signaling cascades." (PMID 32695336, 2020). "The deregulation of the PI3K/Akt/mTOR pathway plays a fundamental role in breast cancer, such that the pharmacological suppression of PI3K/Akt/mTOR signalling showed inhibition of tumor growth in vivo." (PMID 33023525, 2020). "Taken together, our findings suggest that DPP-4 inhibitors potentiate chemotherapy resistance via the induction of ABC transporters by the CXCL12/CXCR4/mTOR/TGFβ signaling pathway in breast cancer cells." (PMID 31991851, 2020). "Dual mTOR inhibitors manifest antitumoral activity through the inhibition of mTORC1 and mTORC2, thus representing a promising strategy for breast cancer treatment." (PMID 33375317, 2020). "Lastly, we examined the effect of inhibition of FAK and mTOR on human basal-like breast cancer cell lines, including CAL-85-1, HCC1806, and MDA-MB-231 cells." (PMID 32493400, 2020). "High levels of phosphatidylinositol-3-kinase (PI3K)/Akt and mammalian target of rapamycin (mTOR) signaling molecules are expressed by breast cancer cells which impair their ability to undergo apoptosis." (PMID 32399389, 2020). "PI3K/Akt/mTOR pathways are a key player in various types of malignant human tumors, such as breast cancer, lung cancer, melanoma, and lymphoma." (PMID 32398958, 2020). "Poor prognosis influenced by ALDH1 was described in the metabolic pathway of PIK3CA/AKT/mTOR of breast cancer concerning grading and metastases." (PMID 32695508, 2020). "In summary, we examined SGLT1 expression in both breast cancer tissues and cell lines and verified that SGLT1 promotes cell proliferation by activation of PI3K/Akt/mTOR signaling in HER2+ breast cancer." (PMID 32377271, 2020). "In both breast cancer cell lines, the levels of p-Akt, p-mTOR, p-p70S6K, and total Akt, mTOR and p70S6K protein decreased to a larger extent after exposure to carbon ions than after exposure to X-rays." (PMID 32239160, 2020). "In patients with breast cancer, PI3K/Akt/mTOR signalling pathway can be a target for diagnostic, prognostic and treatment purposes." (PMID 32807213, 2020). "To further demonstrate the effect of eEF-2K suppression on the sensitivity of mTOR inhibitor against breast cancer cell, we compared the cell viability in response to combined treatment of mTOR inhibitor with eEF-2K siRNA or Beclin 1 siRNA." (PMID 33144562, 2020). "Among them, targeted therapy, such as trastuzumab, CDK4/6 inhibitors, and PI3K/Akt/mTOR inhibitors, significantly prolongs the survival time of patients with breast cancer." (PMID 32518527, 2020). "In 2012, mTOR inhibitors (everolimus) showed a profitable effect on endocrine therapy of breast cancer therapy." (PMID 32461963, 2020). "Effective inhibitors of Akt, mTOR, or both are highly desired and employed in the treatment of TN breast cancer." (PMID 32012648, 2020). "As a part of the present study, we determined that PGRMC1 specifically promotes breast cancer growth by activating the PI3K/AKT/mTOR and EGFR signalling pathway." (PMID 32704174, 2020).